CD4 (CD4 molecule)
Diseases named in the same sentence as CD4 in open-access papers (continued):
Sharing a sentence is not in itself a finding about the gene and the disease.
infection (continued). "We then split the data by volunteer and time point to examine cluster abundance by linear regression and found that in third infection, a single cluster of CD4+ T cells (cluster 10) had expanded at T6." (PMID 40214640, 2025). "The differentiation fate and subsequent functional commitment of CD4+ T helper (Th0) cells are pivotal determinants of infection outcomes in the host immune response against Chlamydia." (PMID 41156830, 2025). "Staining for CD4 and CD8 revealed that both T helper cells and CD8+ T cells were recruited from the peritoneum to the skin upon infection; interestingly, the number of cytotoxic T cells was higher in lesional tissue as compared to CD4+ Th cells." (PMID 40590280, 2025). "BNM-III-170 is a small-molecule CD4 mimetic shown to be inactivating at full Env trimer occupancy but transiently activating at lower occupancies, potentially leading to infection in CD4-negative/CCR5-positive cell lines." (PMID 39912667, 2025). "In vitro studies have demonstrated that HIV can infect “quiescent” CD4+ T cells, although viral replication is inefficient, leading to abortive infections." (PMID 39998960, 2025). "We did find that there was a trend toward more CD1c+ myeloid dendritic cells (mDCs) that expressed DC-SIGN in the lymph nodes in S2 of AHI (P = 0.11), suggesting an increased potential for trans-infection of HIV-specific CD4+ T cells in S2 of AHI." (PMID 39932316, 2025). "used intranasal CPAF plus ADU-S100 adjuvant to induce a CD4+ T cell response and reduce bacterial shedding and duration of infection." (PMID 40433661, 2025). "Infection with T. cruzi expands a CD39+CD73–P2X7+ CD4+ T cell population expressing the granzyme B effector molecule." (PMID 40590226, 2025). "Depleting antibody levels in serum samples remained stable throughout the course of the infection, with concentrations around 1,000 μg/mL for the CD4-depleting mAb and 100 μg/mL for the CD8-depleting mAb." (PMID 40996813, 2025). "Taken together, our data indicate that CARD8 plays a pivotal role in sensing and responding to HIV-1 cell-to-cell infection between primary CD4 T cells and macrophages." (PMID 39229127, 2025). "Interaction between CD74 and MIF enhances the secretion of proinflammatory mediators and promotes unactivated CD4+ T cell infection, leading to viral spreading." (PMID 40427533, 2025). "Tregs, which have been described to contribute to the control of tissue damage in infection, were also investigated in infections with Armenia2008, where CD4+CD8α− Tregs were upregulated at 7 dpi in the blood, spleen, and GHLN." (PMID 41510007, 2025). "G-MDSC and PMN infiltrates were significantly elevated following CD4+ T cell depletion at day 14 after infection, which recapitulated phenotypes in Rag1–/– mice." (PMID 39989461, 2025). "To probe for a possible role of IFN-γ in affecting CD4 T cells responses in other infection settings, we decided to analyze CD4+ T cell polarization in the context of a mouse model for SARS-CoV-2 infection." (PMID 40169810, 2025). "In weanling animals, the proportion of CD4+ T cells amongst PBMCs largely increased throughout infection while, CD4+ T cell proportions were largely flat or trended down in juvenile and adults." (PMID 40360698, 2025). "Our findings suggest that the triggering and amplification of the antiviral pathways by IFN-γ and C/EBPβ/IL-6, respectively, conferred protection from infection of bystander CD4+ T cells upon ATI, resulting in the CA-vDNAlo phenotype." (PMID 40166014, 2025). "In our experimental model, at the peak of infection (14 dpi), the vast majority of splenic granzyme B+ and perforin+ CD4+ T cells expressed CRTAM." (PMID 40590226, 2025). "Cellular immunity in patients with XLA is also important, and we found that pre-infection levels of CD4+ T cells were significantly higher and even more frequently supranormal in the early ambulatory group compared to the hospitalized group." (PMID 41240154, 2025).
infection (continued). "Persisting low-grade infection is characterized by higher frequencies of IL-10-secreting CD4+ effector memory T cells, which agrees with our findings in the severely ill patients in both the acute and convalescent phases." (PMID 40766325, 2025). "Although CD8+ T cells play a relatively minor role in TB immunity compared to CD4+ T cells, they contribute to infection control through cytotoxic mechanisms and cytokine production." (PMID 40895571, 2025). "In either Rag1–/– recipient, adult CD4+T cells differentiated into Th1s similar to levels seen in primary infection." (PMID 40280180, 2025). "Surprisingly, substitution of WT CD4 for CD4-GPI also dramatically reduced infection efficiency (CD4/318)." (PMID 40284914, 2025). "In this study, we investigated theexpression of integrin α4β7 and CCR9 in CD4+ T cellsfollowing infection with PEDV." (PMID 40094365, 2025). "Of note, the abrogation of viral clearance via CD4 + cell depletion also support a negligeable contribution of mouse monocytes and macrophages (and of their phagocytic activity) to infection resolution in our mouse model." (PMID 40920821, 2025). "In terms of cytokine response, CD4+ T cell-specific cytokine responses in the m-m-m group were elevated during the first infection cycle, becoming significant after the second exposure." (PMID 40707512, 2025). "HIV-1 preferentially infects short-lived activated CD4+ T cells; however, studies have shown infection of other cell types." (PMID 41143136, 2025). "Virus-specific CD4+ T cells typically undergo T helper (Th) 1 differentiation and contribute to a type 1 immune response in infection with lymphocytic choriomeningitis virus (LCMV)." (PMID 41488650, 2025). "Firstly, upon infection of CD4+ T cells, HIV proviral genomes integrate into host cell DNA, remaining silent and leading to the creation of a latent reservoir, which is seeded early after primoinfection." (PMID 41373539, 2025). "To exclude the potential impact of defective CD4+ T cell help in cKO mice, we depleted CD4+ T cells using a CD4‐specific antibody prior to LCMV Cl‐13 infection." (PMID 40111008, 2025). "Early CD4+ T-cell immune recovery plays a critical role in reducing infection-related mortality and disease recurrence." (PMID 40270968, 2025). "The rate of productively infected fLX was also higher in CD4 + cell-depleted animals, with 72% of fLX (8/11) showing infection at 12 dpi compared to 50% (4/8) and 33% (2/6) in CD3- and CD8-depleted mice, respectively." (PMID 40920821, 2025). "The specific role of CD4+ T cell responses in protecting against liver stage infection has been poorly investigated." (PMID 40832631, 2025). "It has also been reported that in CHIKV and DENV infection, CD8 T cells are activated during the acute phase of infection whereas CD4 T cells get activated during the chronic stages of infection where they promote B cells and CD8 T cell responses." (PMID 40048709, 2025). "When these neutrophils migrate to lymphoid tissues, they can release the virus and potentially transmit it to CD4+ T cells and other immune cells, amplifying the infection." (PMID 40901106, 2025). "Of our screened cohort, we identified a case of a prolonged EV-C104 infection in an adult immunocompromised patient with uncontrolled HIV infection (CD4 count: 4 cells/mm3)." (PMID 41012611, 2025). "We identified a biphasic pattern of EV release—initial suppression during active infection followed by restoration during and after therapy—most notably affecting the CD4+ and CD14+ subsets." (PMID 40872281, 2025). "Nevertheless, the most efficient combination for infection either Env-753Stop or Env-WT cells remained the CD4-GPI plus CXCR4-318 combination." (PMID 40284914, 2025). "A low dose (~100 bacilli/mouse) aerosol infection of C57BL/6 mice was chosen because CD4+ T cells restrict Mtb growth and protect from lethality under these conditions." (PMID 40489538, 2025).
infection (continued). "In contrast, other effector CD4+ T cell subsets typically leave these lymphoid tissues to migrate toward sites of infection or inflammation." (PMID 39989460, 2025). "In the lymph nodes, both groups experienced CD4+ T cell depletions upon infection, slightly faster in aged RMs." (PMID 40662355, 2025). "Vaccination triggered significant expansion of CD4+ T lymphocytes, which orchestrate anti-parasitic defense through macrophage activation and cytokine-mediated recruitment of immune effectors to infection sites." (PMID 41441646, 2025). "The RSF model was developed based on the top 7 variables ranked by variable importance, including hemoglobin, age at HAART treatment, infection route, white blood cell count, education level, blood glucose, and the CD4 count before HAART." (PMID 40456121, 2025). "Data suggest that immune cell activation accomplished by CD4 + T cells is essential for effective infection containment during Mtb infection." (PMID 40334195, 2025). "The number of patients with CD4 counts below 200/μL was considered an indicator of active infection." (PMID 39869625, 2025). "In mouse models of infection, CD4+ T cells differentiate into Th1/Th17 effector cells in the lung through a MyD88- and inflammasome-dependent process." (PMID 40558085, 2025). "Here, using macrophage and murine infection models, we identify a critical role for CD4+ T cell-dependent cell-mediated immunity in PZA's antitubercular action." (PMID 41416822, 2025). "One key recommendation is the early detection of CM through serum CrAg in patients with HIV presenting at advanced stages of infection (CD4 T-cell count <100 cells/μl), coupled with preventive antifungal treatment for asymptomatic CrAg-positive patients." (PMID 40688526, 2025). "For example, the early window of CD4+ T cell protection that we identified following adoptive transfer in Rag1–/– mice (days –1 to 3 after infection) supports Ag-independent mechanisms given the timescale for induction of Ag-dependent responses." (PMID 39989461, 2025). "CD4+ T-cell depletion was significant in the brain parenchyma, choroid plexus stroma, dura mater, and skull bone marrow 3 weeks after infection compared to uninfected controls." (PMID 40099824, 2025). "Here authors show that long years following mild disease at primary infection, SARSCoV-2 spike-specific CD4 + T cells with distinct phenotypes and T cell receptor clonotypes, associated with viral suppression persist." (PMID 41034205, 2025). "Children of younger ages seem to be more prone to serious infections, and looking at their immune profile, we observed lower percentages of circulating T-cells, with increased CD4/CD8 T-cell ratios." (PMID 41011738, 2025). "Given that KLF2 is involved in immune cell trafficking and adhesion, we used CellChat (v2.1.1) to identify altered ligand–receptor interactions between HIV-1-infected CD4+ T cells and innate immune cells during infection." (PMID 40838493, 2025). "In this study, by isolating CD4+ T cells from chickens at different time points after infection, we found that miR-M6-5p facilitates MDV latency in vivo." (PMID 39840986, 2025). "By 12 dpi and infection resolution, fLX display residual iMO and are enriched in CD4 + PIM and CD163 + CD206 + IM." (PMID 40920821, 2025). "Overall, children developed a SARS-CoV-2–specific CD4+ T cell response early in the course of infection with multiple effector functions, marked by potent production of IFN-γ, TNF, and IL-2, and preferential expression of CXCR3." (PMID 40906527, 2025). "AI-based predictive analytics have been utilized to model CD4+ T cell help requirements in various infection scenarios, thereby refining our understanding of immune memory formation." (PMID 40756816, 2025). "According to univariate analysis, the highest proportion of recent infections was observed among cases with CD4 count at diagnosis ≥350 cells/uL (31.2%), people aged 15–24 years (30.3%), and MSM (29.7%)." (PMID 41011735, 2025).
infection (continued). "Consistent spatial requirements for differentiation of specific CD4+ TM subsets also provide valuable perspectives for identifying common memory precursors under various types of infections and exposures." (PMID 40391228, 2025). "For the immune cells, nine of the 17 included showed statistical differences by infection, including CD4+CCR5+." (PMID 40313463, 2025). "We previously reported that Bl-Eng2–specific CD4+ T cells are recalled to the lungs in substantial numbers upon infection in vaccinated C57BL/6 mice." (PMID 41061037, 2025). "To assess the potential in vivo relevance, we examined the effect of Aβ, α-synuclein, and EF-C fibrils on infection of primary CD4+ T cells, the major HIV-1 target cells in infected individuals." (PMID 39827271, 2025). "Together with our data showing robust and polyfunctional MPXV-specific CD4+ and Tfh responses up to 18 months post-infection, these observations suggest that coordinated CD4+, Tfh, and CD8+ T cell immunity underpins durable protection against mpox." (PMID 41345407, 2025). "Differences in antigen recognition pathways can lead to the differentiation of CD4+ T cells into various T-cell subtypes, each producing distinct cytokines that play different roles in the anti-infection process." (PMID 39831768, 2025). "We analyzed the levels of CD4 T-cells induced by vaccination, infection, and their combination in immunocompromised and healthy individuals using the FASCIA method in fresh whole blood." (PMID 41280926, 2025). "The condensing of the granuloma likely represents the removal of CD68+ phagocytes that successfully cleared fungal cells, while the recruited CD4+ T cells remain surrounding areas of ongoing infection." (PMID 39807873, 2025). "HIV latency is established very early during acute HIV infection, either through direct infection of resting memory CD4+ T cells or through infection of actively replicating CD4+ T cells that are later induced to a resting state." (PMID 40438119, 2025). "Overall, these findings indicate that 17ZR101-infection leads to a complex landscape of CD4 T cells." (PMID 40096073, 2025). "After infection, T cells are activated; of these, CD4+ and CD8+ cells play an important role in host immunity against N. caninum, with CD4+ cells being more effective than CD8+ cells." (PMID 39930494, 2025). "We observed that both prior to and after infection, 40RD mice displayed reduced numbers of B cells, CD4 T cells, and CD8 T cells compared to controls (Supplemental 1)." (PMID 39229137, 2025). "We demonstrated successful infection of resting and activated CD4 + T-cells using Morpheus-V5 pseudotyped with either X4, R5 or dual tropic envelope proteins." (PMID 40754007, 2025). "Spike-specific memory CD4+ T cells were maintained for at least 6 months after infection in the majority of children (54%) and adults (65%)." (PMID 40906527, 2025). "SupT1 cells were infected with NL4–3 or NLRev_IRES_Nef viruses at an MOI of 0.005 and then stained for intracellular p24 and surface CD4 expression at 8 days post-infection." (PMID 39829859, 2025). "The polyfunctionalities of these cells were also not markedly altered, although there was a significant change in the overall functional profile of SARS-CoV-2–specific CD4+ T cells in lactating individuals following breakthrough infection." (PMID 40693463, 2025). "Rhesus macaques were either depleted of CD4+ T cells prior to infection or left undepleted as controls." (PMID 41295476, 2025). "Following infection, neonatal mice had a significantly increased number of CD4+ T cells expressing Tbet, the canonical marker of Th1s, compared to mock-infected neonates." (PMID 40280180, 2025). "A significant induction of IFN-γ–producing spike-specific CD4+ T cells was observed for children in the acute phase of infection (3-fold, P = 0.01)." (PMID 40906527, 2025).
infection (continued). "youth with HIV (YWH) virally suppressed on ART early in infection before CD4 T cell decline with fewer comorbidities compared to adults represent a critical population for identifying markers associated with viral control and predictors of viral breakthrough." (PMID 39996757, 2025). "Additionally, the emerging R476K mutation in the CD4 contact residue in T/F subtype A1 may enhance viral entry in acute infection while the recurrent R476 in historical counterparts may sustain long-term infection." (PMID 40831640, 2025). "CD4 + T cells are recruited to the initial site of infection, which spreads locally within the tissue." (PMID 40386405, 2025). "By infection of CD4+ T cells, HIV-1 infiltrates and subverts this important immune cell type necessary to orchestrate the immune response against pathogens." (PMID 40911682, 2025). "Specifically, the dynamic equilibrium among CD4+ T cell subsets, such as T helper (Th) 1, Th2, Th17, and regulatory T (Treg) cells, is crucial for regulating the post-infection immune response." (PMID 41425878, 2025). "We had previously demonstrated that infection with B. pertussis induces IL‐10‐secreting CD4+ Treg cells." (PMID 40629997, 2025). "Conclusions from our experiments are that neither of these genes, though strongly upregulated transcriptionally at various phases of effector and memory differentiation, play any role in CD4+ T cells during infection with blood-stage Plasmodium parasites." (PMID 40132035, 2025). "To characterize the proviral landscape in naive and memory T cell populations, we therefore performed ISA using HIV+ MDA products from participant 1001, selected for the high frequency of infection of naive CD4+ T cells." (PMID 40048262, 2025). "The cytokines produced by CD4 + Th cells fight infection and regulate inflammation, a necessary process to relieve and balance the stress generated." (PMID 40743218, 2025). "Infection with the gut‐dwelling nematode H. polygyrus results in up‐regulation of surface CD154 expression on peritoneal CD4+ T cells, suggestive of antigen presentation at this site." (PMID 41388224, 2025). "The stochastic model is used to quantify the impact of MOI and TIP-2 on the net HIV-1, TIP-2 and heterozygous particles release by co-infected CD4+ T cell during 36 h post infection." (PMID 41157648, 2025). "SARS-CoV-2-specific CD4+ T cells persist across disease stages, showing Th1 polarization during acute infection and into convalescence, as demonstrated by multiple immunological studies." (PMID 40806391, 2025). "We also discuss the challenges and prospects for identifying common precursor of specific CD4+ TM cells under various types of infections and exposures." (PMID 40391228, 2025). "Using multiplex immunofluorescence, we identify an inverse relationship between CD4+ T cells and neutrophils within lung lesions that is dynamic over the first weeks of infection and dependent on early type I IFN signaling in both C57BL/6 and C3HeB/FeJ mice." (PMID 40986319, 2025). "We also found that increased frequency of these CD25+CD4 T cells and CD4 Tregs (CD25+CD127-) with a CM T cells were protective against infection." (PMID 40475763, 2025). "It is well known that immunity to C. trachomatis involves many cell types, but CD4+ T cells play a key role in protecting the host during natural infection." (PMID 39903705, 2025). "Holm and colleagues have demonstrated that the infection of primary T cell cultures with the CXCR4-tropic HIV-1 variant ELI6, induce activation of CD4+ and CD8+ T cells, which subsequently undergo apoptosis." (PMID 40709192, 2025). "We transferred into congenic recipients either CD4-Cre Maf(f/f) PbTIIs (KO), or WT control PbTIIs from Maf(f/f) PbTII littermates, examining splenic responses 7-days post-infection." (PMID 40132035, 2025).